MTOR (mechanistic target of rapamycin kinase)
Diseases named in the same sentence as MTOR in open-access papers (continued):
Sharing a sentence is not in itself a finding about the gene and the disease.
cancer (continued). "We demonstrated that Akt inhibitor MK-2206 and MEK inhibitor U0126 also synergized with #43, providing a rationale for the combination of #43 with Akt/mTOR or MEK/ERK inhibitors in cancer treatment." (PMID 35662690, 2022). "This new generation mTOR inhibitors has been introduced into clinical trials mainly for the treatment of various cancers." (PMID 35883796, 2022). "The PI3K/AKT/mTOR pathway regulates several of these functions, and has been implicated in CRT resistance in various cancers and Mutations affecting this pathway genes are frequently detected in cancer." (PMID 35860583, 2022). "In vitro and in vivo, rapamycin which is an immunosuppressant agent actively suppresses the activity of mTOR and reduces cancer cell growth." (PMID 36109789, 2022). "It has been confirmed that curcumin arrests cancer cells in G2/M phase by potentiating Erk1/2 and inhibiting Akt together with its corresponding downstream molecules (mTOR and S6K1) in Ras-activated HAG-1 human adenocarcinoma cells." (PMID 36439106, 2022). "In lung cancer, prostate cancer, breast cancer, and other malignant tumors, the activity of mTOR has been found to be significantly increased." (PMID 36507521, 2022). "Among all, 33 displayedpotential anti-GBM activity, with IC50 = 2.5 μM.Further, the docking studies and biological studies revealed thatthe 33 possibly inhibits the PI3K/mTOR kinase which isa responsible cofactor of the cancer development." (PMID 35786935, 2022). "The antitumor effect of mTOR inhibitors is mainly achieved by inhibiting this pathway in cancer cells, but the cancer suppressor effect will be offset by drug harmful results on TAMs." (PMID 35874739, 2022). "The mTOR expression was reduced in patients with a cancer spreading; in contrast, AMPK grew with the tumor size." (PMID 35877414, 2022). "Rapamycin, a specific inhibitor of MTOR, has been widely used as an immunosuppressant in organ transplant patients, and its clinical application has been recently expanded to cancer therapy." (PMID 35159256, 2022). "We observe that mTOR suppression promotes the induction of persisters in various cancer cells undergoing chemotherapy and dampens therapeutic efficacy." (PMID 36396656, 2022). "PI3K/AKT/mechanistic target of the rapamycin kinase (mTOR) is responsive to maintain a redox metabolism in cancer." (PMID 36139919, 2022). "Mechanistically, lomitapide directly inhibits the kinase activity of mTOR and induces autophagy, thereby suppressing growth while increasing cancer cell death." (PMID 35831271, 2022). "The PI3K/AKT/mTOR pathway is one of the most frequently activated pathways in several types of cancer and the link between PI3K/AKT/mTOR pathway deregulation and endocrine resistance in BC is well established." (PMID 36045911, 2022). "Despite recent improvements in the research of mTOR signaling in cells, notably its development as a therapeutic target for cancer treatment, more work must be done to completely comprehend the relevance of mTOR and its functions in cell biology and illness." (PMID 36109789, 2022). "The in vivo study further proved the functions of the MALAT1/MYBL2/mTOR axis in cancer proliferation and glucose metabolism in PCa cells." (PMID 35557985, 2022). "mTOR inhibitors, PI3K inhibitors, Akt inhibitors, and dual PI3K/mTOR inhibitors have all been studied as monotherapy or in combination with other inhibitors in the treatment and prevention of cancer." (PMID 35402264, 2022). "Mapping of common differential transcripts to the KEGG cancer signaling pathway noted that glutathione metabolism, the mTOR signaling pathway, protein digestion and absorption, and other metabolic-related pathways changed significantly." (PMID 35416493, 2022). "Both PI3K and mTOR inhibitors suppress cancer cells under laboratory conditions, and some of these less toxic inhibitors have been validated in clinical trials and thus have the potential to act as promising new anticancer agents." (PMID 35586809, 2022).
cancer (continued). "In cancer models of mice, inhibiting mTOR substantially decreased intestinal carcinogenesis and increased survival." (PMID 36293326, 2022). "Accordingly, rapamycin, as well as CR and PR, is capable of reducing mTOR activation in tumour cells and reducing cancer incidence and tumour size, probably due to an enhancement of autophagy and a reduction in protein synthesis." (PMID 35955882, 2022). "While mTOR inhibition alone has clear efficacy in some types of cancer, preclinical studies demonstrate strong rationale for combining mTOR inhibitors with other drugs, including OVs." (PMID 36221123, 2022). "We found that simultaneous blockade of mGluR1 and PI3K/mTOR pathways resulted in decreased cancer cell survival and tumor growth." (PMID 35086953, 2022). "A recent study associated MTOR overexpression in the TKI inhibitors resistance process, demonstrating that stress-induced mutagenesis contributes to adaptive evolution in cancer for drug resistance." (PMID 35011716, 2022). "KEGG analysis revealed the involvement of the hub genes in different signaling pathways such as estrogen, FoxO, IL-17, cancer pathways, mTOR, JAK-STAT, VEGF, PI3K-Akt, Ras, and Toll-like receptor." (PMID 36351994, 2022). "Previous research has shown that the mTOR pathway's overactivation plays a significant role in the development of cancer because of its impact on proteins." (PMID 36507521, 2022). "The phosphatidylinositol 3-kinase (PI3K)/Akt/mammalian target of the rapamycin (mTOR) signaling pathway is activated in human cancers, which participates in many cellular processes, such as cell survival, metastasis, autophagy, metabolism, and angiogenesis." (PMID 36072472, 2022). "One study showed that the mechanism of autophagy activation by a halofuginone-induced amino acid response in cancer cell lines is the proteasomal degradation of mTOR." (PMID 35955944, 2022). "Rapamycin and its analogs (rapalogs, including everolimus, temsirolimus, and ridaforolimus) are FDA-approved as mTOR inhibitors in clinical settings such as cancer and autoimmunity." (PMID 33880473, 2022). "The mTOR signaling system, in particular, is involved in apoptosis, cell cycle, and cancer cell proliferation." (PMID 36428613, 2022). "mTOR is a key kinase downstream of PI3K/Akt that plays a role in regulating cancer cell growth, proliferation, survival, and even metastasis." (PMID 35586809, 2022). "The PI3K/AKT/mTOR pathway is involved in the onset and progression of several cancers, among which is RMS." (PMID 35566091, 2022). "Tetrandrine has been reported to induce autophagy in an mTOR-dependent manner, as well as to inhibit the lysosomal degradation of autophagosomes in cancer cells." (PMID 35897724, 2022). "The PI3K/Akt/mTOR axis, which is involved in cancer cell proliferation, differentiation and cellular metabolism, is frequently activated in many cancers and is one of the most significant molecular pathways in mRCC." (PMID 36474188, 2022). "The PI3K-Akt-mTOR pathway is a central regulator of glycolysis that promotes cancer metabolism and proliferation." (PMID 35281118, 2022). "Given that elevated PI3K/mTOR signaling is a commonality among all tumor types, Glut1 is often overexpressed in cancer, and the expression of this transporter is correlated with poor patient outcomes across tumor types." (PMID 34239083, 2022). "PF-04691502 is a relatively novel dual PI3K/mTOR inhibitor that exerts inhibitory effects against various cancer cells." (PMID 35783514, 2022).
cancer (continued). "P2RY2 was reported to enhance cancer cell glycolysis by PI3K/AKT-mammalian target of rapamycin (mTOR) signaling, resulting in PAAD progression." (PMID 36428619, 2022). "As a critical modulator of autophagy, PI3K/AKT/mTOR-mediated autophagy is involved in many cancers, including PDAC." (PMID 35521536, 2022). "As Food and Drug Administration-approved inhibitors of mammalian target of rapamycin (mTOR) kinase, these macrolide compounds are used therapeutically to inhibit the processes of cancer, autoimmunity, graft versus host disease, atherosclerosis, and aging." (PMID 33880473, 2022). "mTORC2 also increases cell proliferation and survival through the regulation of protein kinases, including AKT, which overall provides significant motivation for additional studies on therapeutic targeting of mTOR complexes in cancer." (PMID 36077798, 2022). "The pro-survival kinase mTOR (mammalian target of rapamycin) supports tumor development and is frequently activated in cancer." (PMID 34907345, 2022). "The mammalian target of rapamycin (mTOR) is a protein kinase that plays a crucial role in cell growth and homeostasis, which is often dysregulated in cancer cells, and upregulated in cisplatin resistant and aggressive HNSCCs." (PMID 36558560, 2022). "The phosphatidylinositol 3-kinase (PI3K)/AKT/mammalian target of rapamycin (mTOR) signaling pathway aberrant activation regulated cellular processes including proliferation, metabolism, apoptosis and metastasis in many cancer types 20-22." (PMID 35912013, 2022). "Many studies reported that chemoresistance is closely correlated with the activation of the PI3K/Akt/mTOR pathway in cancer cells." (PMID 35783514, 2022). "PI3K/AKT/mTOR pathway is a classical pathway in cancer, and this pathway inhibitors are effective and safe in patients with locally advanced, metastatic or recurrent EC." (PMID 35259044, 2022). "In recent years, the mammalian target of rapamycin (mTOR) inhibitors, rapamycin, and its analogs have become promising therapeutic drugs against cancer because of mTOR’s role in tumor progression." (PMID 35444553, 2022). "Nevertheless, the PI3K/AKT/mTOR cascade includes a complex network of biological events, needing more sophisticated approaches for their use in cancer treatment." (PMID 35565291, 2022). "Its overexpression in OSCC cells would largely increase the malignancy of the cells in vitro and in vivo and regulate the malignant behavior of cancer cells through the PI3K/mammalian target of rapamycin (mTOR)/Akt and MAPK pathways." (PMID 36230547, 2022). "This review highlights the importance of the PI3K/AKT/mTOR pathway in cancer genesis and progression and summarizes inhibitors of this axis for cancer prevention and treatment." (PMID 35402264, 2022). "Here, the authors identify the mTOR pathway as a determinant of chemosensitivity and demonstrate that inhibition of mTOR promotes the persistence of a chemotherapy-resistant cancer-cell subpopulation." (PMID 36396656, 2022). "In this study, we reported an unexpected function of NOP56 in metabolic stress response and a previously unrecognized metabolic synthetic lethality by targeting NOP56 and mTOR in KRAS-mutant cancers." (PMID 35039048, 2022). "In the twenty most significantly enriched KEGG pathways, focal adhesion, gap junction, mTOR signaling pathway, and proteoglycans in cancer, are involved in tumor growth and metastasis." (PMID 35433481, 2022). "TBMS-1 selectively binds mTOR kinase and suppresses mTORC1 activation to prevent PD-1/PD-L1 interactions and improve T cell cytotoxicity towards cancer cells." (PMID 35910383, 2022). "Subnet 2 was annotated to Wnt signaling pathway, mTOR signaling pathway, Pathways in cancer, Proteoglycans in cancer and other tumor-related pathways." (PMID 34998434, 2022). "mTOR inhibitors can reduce the tumor resistance to IR and increase the radiosensitivity of different cancer cells." (PMID 35485300, 2022).
cancer (continued). "Synthetic compounds also act as cancer-preventive therapeutics targeting the mTOR signaling pathway." (PMID 36428613, 2022). "The PI3K/AKT/mTOR pathway is an essential intracellular signaling pathway that regulates the processes of cancer diseases including cell metabolism, cell proliferation, apoptosis, and gene expression." (PMID 36313041, 2022). "Blocking the Akt/mTOR signaling pathway reversed RAD21 overexpression-induced cancer progression and drug resistance." (PMID 35860572, 2022). "The cancer cell-DRG coculture system demonstrated that activating mTOR increases the cancer cell invasion index and DRG axon growth index." (PMID 35449152, 2022). "Akt, also known as the PKB (protein kinase B) and mTOR (mammalian target of rapamycin) signaling pathway, is the most frequently activated signaling network in human cancers." (PMID 35123502, 2022). "It has been reported that SP, after binding to the NK-1R, activates the mammalian target of rapamycin (mTOR) signaling axis in cancer cells and enhances tumor cell growth and metastasis." (PMID 35434136, 2022). "This issue represents a major drawback of the trial, as the mTOR pathway is modulated by multiple cascades in cancer, including HCC; in addition, HCC is a highly heterogeneous disease." (PMID 35166233, 2022). "The PI3K/Akt/mTOR pathway is one of the most complex regulatory networks in the human body, and the abnormality of main components stimulated the occurrence of cancer." (PMID 35392233, 2022). "Beyond acting as a metabolic integrator, insulin coordinates cancer cell metabolism, proliferation and motility through its action on Akt/mTOR axis, lipogenesis and mitochondria." (PMID 36012397, 2022). "Deeper hierarchical clustering of previously identified clusters grouped cluster 7, 36,37,42,47,48,50,53,55 into a single supercluster with over-representation of cancer-specific pathways such as mTOR pathways and NOD-like signalling pathways." (PMID 35773268, 2022). "Quercetin was shown to induce mitochondria-mediated apoptosis in cancer cells through the inactivation of Akt-1 in the Akt/mTOR axis, a change that in AML cells correlated with a drop in MMP." (PMID 35563141, 2022). "Clinical studies have found that mTOR activity is significantly enhanced in most patients with malignant tumors and is closely related to adverse factors, such as tumor recurrence and progression." (PMID 36397350, 2022). "MiR-99a/b has been implicated as a tumor suppressor frequently downregulated in human cancers, and plays an important role in regulating mTOR signaling pathway." (PMID 35328346, 2022). "Evidence indicates that the AKT/mTOR signaling axis significantly regulates the malignant phenotypes of cancer cells, such as proliferation, metastasis, and EMT, and is related to the chemoresistance and radioresistance in various tumors." (PMID 35103094, 2022). "Several autophagy-inducible drugs, including Tamoxifen and mTOR protein inhibitors, have been used in the clinical treatment of various malignant tumors." (PMID 35847371, 2022). "This defect was mitigated/reversed by treatment with rapamycin, further supporting the role of mTOR-inhibition in a cancer checkpoint." (PMID 36052376, 2022). "Drug sensitivity analysis shows that in contrast to the association of YAP1/EGFR/MAP2K1 with drug resistance, high expressions of mTOR are favorable to cancer chemotherapy." (PMID 35655775, 2022). "The mTOR signaling pathway is essential for cell proliferation and survival, and in many types of cancers, mTOR is typically abnormally activated due to metabolic changes or mutations in upstream regulatory factors." (PMID 35517785, 2022). "Curcumin has been shown to induce cancer cell autophagy by inhibiting the PKB/mammalian target of rapamycin (mTOR)/p70S6 pathway and MAPK1/2 pathway and inhibits signalling protein STAT3 by suppressing the IL6-mediated phosphorylation of STAT3." (PMID 35663647, 2022).
cancer (continued). "Regarding autophagy, the relationship between mTOR and autophagy was first discovered in cancer, and studies have found that mTOR activation is negatively correlated with autophagy." (PMID 36012464, 2022). "Li and colleagues (2020) discovered that andrographolide facilitates downregulation of the PI3K/Akt/mTOR pathway and inhibits glycolysis, a vital process that is needed for the survival and proliferation of cancer cells." (PMID 35682652, 2022). "It has been demonstrated previously that the PI3K/AKT/MTOR signaling pathway is actively involved in the regulation of cancer cell proliferation, metastasis, survival, as well as the angiogenesis." (PMID 35155433, 2022). "KEGG pathway analysis demonstrated that these genes were mainly involved in circadian rhythm, ferroptosis, mTOR signaling pathway, phagosome, central carbon metabolism in cancer, and longevity regulating pathway." (PMID 36238640, 2022). "Resveratrol inhibited the mTOR signaling pathway in several cancer cells (HeLa, HepG2, and MCF-7) resulting in the downregulation of the mRNA and protein levels of PKM2." (PMID 36339566, 2022). "Aberrant activation of PI3K/Akt/mTOR signaling pathway is considered one of the major factors in the development of many cancers." (PMID 37304410, 2022). "Subsequently, activated AKT phosphorylates downstream protein effectors, including the mammalian target of rapamycin (mTOR), which has an established role in human cancers." (PMID 35255942, 2022). "In this context, we believe that the small molecule amino flavonoid fusarochromanone (FC101) possesses remarkable potential as an mTOR pathway modulating agent for use in cancer drug discovery." (PMID 36428475, 2022). "Conversely, activation of the mTOR pathway increases chemosensitivity in vitro and in vivo and predicts better survival among various human cancers." (PMID 36396656, 2022). "First, a pan-cancer search of alteration frequency focused on two major cancer kinases, mTOR and AMPK, was conducted and compared to HUNK." (PMID 36551828, 2022). "For example, current cancer autophagy therapies aim to target the mammalian target of rapamycin (mTor), a protein that has an inhibitory effect in the process, and which is also involved in other cellular processes." (PMID 36569125, 2022). "The PI3K/AKT/mTOR pathway, which plays an important role in survival and proliferation of cancer cells, is also activated by IL-6." (PMID 35470375, 2022). "The mTOR pathway is known to be manipulated in cancer, and components of the pathway have been shown to degrade p19ARF to promote proliferation in MEFs." (PMID 34994382, 2022). "For this reason, many preclinical investigations on the effects of combining mTOR inhibitors with cancer vaccines have been conducted." (PMID 36428613, 2022). "Several studies have shown that excessive accumulation of ERBB2 is one of the key triggers of abnormal excitation of the PI3K/Akt/mTOR signaling axis and is involved in the regulation of VM formation in cancer cells." (PMID 37304410, 2022). "mTOR and Akt inhibitors are currently undergoing clinical trials to treat various cancers and other metabolism-related disorders." (PMID 36041631, 2022). "Although it has been reported that amino acid metabolism generally affects the mTOR signaling pathway and proliferation in various carcinomas, the possibility of the presence of cell-specific or cancer-specific amino acid metabolism has not been ruled out." (PMID 35955892, 2022). "In our in vitro analysis, we found higher mTOR (especially mTORC2) activity and metabolic marker expressions in carcinoma cell lines as compared to the HK-2 cells, according to the higher proliferation capacity of the cancer cells." (PMID 36142502, 2022).